LINC02357 (long independently transcribed non-coding RNA 2357)
Gene: Long non-coding RNA gene on chromosome 4 (26,064,298 to 26,104,947, forward strand). Ensembl gene ENSG00000283314.
Diseases named in the same sentence as LINC02357 in open-access papers:
LINC02357 is named in the same sentence as 1 disease in open-access papers, as found by Europe PMC text mining. Sharing a sentence is not in itself a finding about the gene and the disease.
LINC02357 shares sentences with these, for which no sentence is quoted: hypothyroidism (1 paper).